MZT2A (mitotic spindle organizing protein 2A)
Description:
Required for the recruitment and the assembly of the gamma-tubulin ring complex (gTuRC) at the centrosome. The gTuRC regulates the minus-end nucleation of alpha-beta tubulin heterodimers that grow into microtubule protafilaments, a critical step in centrosome duplication and spindle formation.
Synonyms: FAM128A; MOZART2A
Tractability: Small molecule: a structure with a bound ligand is known. PROTAC: ubiquitination databases record sites on it.
Gene: Protein-coding gene on chromosome 2 (131,464,900 to 131,492,743, reverse strand). Ensembl gene ENSG00000173272.
Subcellular location: Cytoplasm, cytoskeleton, microtubule organizing center, centrosome; Cytoplasm, cytoskeleton, spindle
Subcellular location (Human Protein Atlas): Centrosome; Cytosol
Pathways (Reactome):
Cell Cycle: Recruitment of NuMA to mitotic centrosomes; Recruitment of mitotic centrosome proteins and complexes
Gene Ontology:
Molecular function: protein binding
Biological process: microtubule nucleation
Cellular component: centrosome; cytosol; gamma-tubulin complex; gamma-tubulin ring complex; spindle
Genetic constraint (gnomAD): Loss-of-function variants: 8 observed, 9.56 expected, observed/expected ratio (o/e) 0.84, 90% interval 0.49 to 1.5. That is too few expected variants to judge how well the gene tolerates losing a copy. Missense variants: 181 observed, 182.74 expected, observed/expected ratio (o/e) 0.99, 90% interval 0.88 to 1.12. Synonymous variants: 88 observed, 85.52 expected, observed/expected ratio (o/e) 1.03, 90% interval 0.87 to 1.23.
Homologues: Orthologues: macaque MZT2B (92% identical), dog MZT2B (90% identical), mouse Mzt2 (68% identical), rat Mzt2b (67% identical), tropical clawed frog mzt2b (49% identical), zebrafish mzt2b (47% identical). Paralogues in human: MZT2B (96% identical).
Diseases named in the same sentence as MZT2A in open-access papers:
MZT2A is named in the same sentence as 3 diseases in open-access papers, as found by Europe PMC text mining. Sharing a sentence is not in itself a finding about the gene and the disease. The quoted sentences say what the papers report.
gastric cancer (1 paper, 2025). A primary or metastatic malignant neoplasm involving the stomach. "To date, limited studies have linked MZT2A to tumorigenesis, primarily in lung and gastric cancers." (PMID 40717581, 2025). "Current evidence linking MZT2A to tumorigenesis is limited and has mainly focused on lung and gastric cancers." (PMID 40717581, 2025).
tumor (4 papers, 2020 to 2025). "Our objective was to investigate the association between MZT2A expression and patient outcomes, as well as to explore its potential involvement in tumor biology and the immune microenvironment." (PMID 40717581, 2025). "Using paired tumor and normal samples from TCGA, we assessed MZT2A expression across multiple cancer types." (PMID 40717581, 2025). "In this study, we analyzed MZT2A expression across multiple cancer types using paired tumor and normal tissue samples from The Cancer Genome Atlas (TCGA)." (PMID 40717581, 2025). "However, mechanisms on how MZT2A influences tumor prognosis and CD8+ T-cell infiltration should be further explored." (PMID 34650911, 2021). "Collectively, these findings suggest that MZT2A is involved in immune cell infiltration and the tumor microenvironment, may contribute to KIRC progression, and is overexpressed in cases with poor prognosis, supporting its potential as a diagnostic and prognostic biomarker." (PMID 40717581, 2025). "Collectively, these findings suggest that MZT2A is involved in immune cell infiltration and the tumor microenvironment, may promote KIRC progression, and is overexpressed in cases with poor outcomes, supporting its potential as a diagnostic and prognostic biomarker." (PMID 40717581, 2025). "MZT2A is a key gene involved in mitotic spindle formation and promotes cell proliferation, while S100A6 and S100P are well-known marker genes for tumor cells." (PMID 39883515, 2024).
MZT2A also shares sentences with these, for which no sentence is quoted: cancer (1 paper).